GNAQ (G protein subunit alpha q)
Diseases named in the same sentence as GNAQ in open-access papers (continued):
Sharing a sentence is not in itself a finding about the gene and the disease.
Sturge-Weber syndrome (22 papers, 2013 to 2026). Sturge-Weber syndrome (SWS) is a rare congenital neurocutaneous disorder characterized by facial capillary malformations and/or cerebral and ocular ipsilateral vascular malformations that result in variable degrees of ocular and neurological anomalies. "Sturge-Weber syndrome (SWS) is a rare congenital neurocutaneous disorder caused by somatic mutations in the GNAQ gene, resulting in capillary-venous malformations involving the brain, skin, and eyes." (PMID 41137931, 2025). "Mosaic mutations in genes GNAQ or GNA11 lead to a spectrum of diseases including Sturge-Weber syndrome and phakomatosis pigmentovascularis with dermal melanocytosis." (PMID 37802294, 2024). "Sturge-Weber syndrome is a complicated disease in which GNAQ mutations drive progressive capillary vessel dilation and dysfunction in skin, eye, and brain tissue." (PMID 36405075, 2022). "Sporadic somatic mutations in the G protein subunit alpha Q on chromosome 9 cause Sturge-Weber syndrome." (PMID 35592185, 2022). "Variation in GNAQ is associated with Sturge-Weber syndrome, a hereditary vascular malformation syndrome which can lead to deposits of calcium (calcification) in the brain." (PMID 33175840, 2020). "We identified p.Arg183Gln mutations in GNAQ, encoding the G protein alpha subunit Gαq, as the cause of both Sturge-Weber syndrome (OMIM #185300) and port-wine stain birthmarks (OMIM #163000)." (PMID 25513881, 2014). "Somatic activating mutations in guanine nucleotide-binding protein G(q) subunit alpha (GNAQ) gene have been found to be associated with Sturge-Weber syndrome." (PMID 24207015, 2013). "Besides variants in genes of the PI3K/AKT or RAS/MAPK pathways, somatic mosaicism in GNAQ or GNAS is associated with monogenic disorders such as Sturge-Weber syndrome (GNAQ variants) or McCune-Albright syndrome (GNAS variants)." (PMID 38835734, 2023). "Sturge-Weber syndrome—In Sturge-Weber syndrome a somatic mutation in GNAQ (c." (PMID 37060495, 2023). "Mutations in GNAQ underlie vascular malformations, including Sturge-Weber disease." (PMID 35053574, 2022). "Mosaic variants in genes GNAQ or GNA11 lead to a spectrum of vascular and pigmentary diseases including Sturge-Weber syndrome, in which progressive postnatal neurological deterioration led us to seek biologically targeted therapeutics." (PMID 37802293, 2024). "The finding of CM on the frontonasal placode in a child should prompt ophthalmologic examination and contrast-enhanced MRI that is recommended when the child is 1 year old Mosaic mutations in GNAQ gene has been found to cause both Sturge-Weber syndrome (SWS) and isolated CMs." (PMID 36533238, 2022). "GNAQ mutations have also been identified in Sturge-Weber syndrome (SWS) and CM." (PMID 33634164, 2020). "Sturge-Weber syndrome is a rare neurovascular disorder associated with seizures, capillary malformation, cognitive impairments, and stroke-like episodes (SLE), arising from a somatic activating mutation in GNAQ." (PMID 35209959, 2022). "This hypothesis was generated by the rare concurrent description of PPV with Sturge-Weber syndrome (SWS), a vascular disorder with no pigmentary phenotype recently found to be the result of postzygotic mosaicism for activating mutations in GNAQ." (PMID 26778290, 2016).
lung carcinoma (13 papers, 2013 to 2025). "Our study provides evidence for the tumor-suppressive role of GNAQ in lung cancer and sheds light on the molecular mechanisms underlying the regulatory interactions between GNAQ and ZO-1/2." (PMID 37240145, 2023). "We further explored the molecular pathways associated with ZO-1 and ZO-2 in lung cancer and identified the G protein subunit alpha q (GNAQ) as a potential interacting partner, belonging to the G protein family of signaling molecules." (PMID 37240145, 2023). "Knockdown of GNAQ has been shown to induce mesenchymal stem cell like properties in lung cancer cells." (PMID 39324009, 2024). "As a tumor-suppressive function, GNAQ depletion induces tumor cell growth, and metastasis from the bone to the lung promotes cancer stem cell-like properties in lung cancer cells." (PMID 37240145, 2023). "By influencing the MAPK signaling pathway and the epithelial-mesenchymal transition, GNAQ enhances lung cancer cell proliferation and invasion." (PMID 35601407, 2022). "The knockdown of the inhibitory guanine nucleotide-binding protein G(q) subunit alpha (GNAQ) in lung cancer cells promotes the RANKL expression and, therefore, osteoclastogenesis due to an enhanced AKT/NFKB signaling." (PMID 34064589, 2021). "Notably, the analysis of TCGA pan-cancer datasets revealed that GNAQ expression was downregulated in most cancer types including lung cancer." (PMID 37240145, 2023). "Conversely, overexpression of GNAQ in A549 cells resulted in increased expression of ZO-1 and ZO-2, indicating that their expression was controlled by GNAQ, an upstream regulatory molecule of ZO-1, and ZO-2 in lung cancer." (PMID 37240145, 2023). "Collectively, our findings suggest that the GNAQ-ZO-1/2 axis plays a crucial role in lung cancer progression and may provide a novel strategy for treating lung cancer and improving patient outcomes." (PMID 37240145, 2023). "Moreover, we identified GNAQ as a potential partner of ZO-1 and ZO-2 in lung cancer." (PMID 37240145, 2023). "We also identified G protein subunit alpha q (GNAQ) as a potential ZO-1- and ZO-2-specific activator through analysis of correlated genes with the TCGA lung cancer database." (PMID 37240145, 2023). "To select specific candidate upstream molecules, we conducted a reference search and found evidence that the GNAQ gene is a tumor suppressor that inhibits EMT, especially in lung cancer." (PMID 37240145, 2023). "Three regions: 3p14.2 (deletion), 9p21.2q21.31 (amplification), and 20q13.12 (amplification) were commonly found in HN4 and HN31 as the same cluster in our analysis, and five genes (FHIT, MMP9, GNA14, GNAQ, and PSAT1) were involved in tumorigenesis in lung cancer and colon cancer." (PMID 27501229, 2016).
vascular malformation (12 papers, 2020 to 2026). A non-neoplastic disorder that is the result of defects of vascular morphogenesis. "First, driver oncogenic mutations are more common in hemogenic vascular malformations (GNAQ, PI3 kinase, tie-2, Braf, and ras) than in lymphatic vascular lesions." (PMID 35053574, 2022). "Vascular malformations contain driver mutations in GNAQ, HRas and phosphoinositol-3 kinase subunits, underlying Sturge-Weber disease, and other vascular malformations." (PMID 32046305, 2020). "While SWS arises from vascular malformations linked to GNAQ mutations, and DLE represents an autoimmune process triggered by environmental factors such as UV exposure; shared inflammatory and vascular mechanisms may underlie their intersection." (PMID 41383537, 2025). "For example, MEK inhibitors may be useful in managing vascular malformations or benign proliferations like hemangiomas associated with GNAQ/GNA11 mutations." (PMID 39518110, 2024). "Mutations in PIK3CA, TEK, GNAQ, and GNA11 have been identified in various types of vascular malformations and hemangiomas." (PMID 40428263, 2025). "And recurrently mutated genes were identified in several vascular malformations as well including TEK/TIE2 mainly in venous malformations, GNA11/14 mainly in vascular tumors, KRAS/NRAS/RASA1/HRAS mainly in AVMs, GNAQ, IDH1/2, AKT1, PTEN and PIK3CA." (PMID 34736485, 2021). "Our findings demonstrate that GNA gene (GNAQ, GNA11, GNA14) mutations are a major pathogenetic event in benign vascular proliferations, however, primarily in hemangioma and not vascular malformations." (PMID 34040639, 2021).
capillary malformation (8 papers, 2020 to 2026). "Capillary malformations (CMs) are congenital vascular lesions caused by somatic mutations in the GNAQ gene, most frequently resulting in a p.R183Q substitution in the Gαq protein in endothelial cells." (PMID 41636844, 2026). "GNAQ (a G-protein subunit alpha q) is required for platelet activation, and its mutation in endothelial cells leads to capillary malformations." (PMID 38145212, 2023). "GNAQ, encoding the G protein subunit alpha q, is somatically mutated in isolated capillary malformation termed as port-wine stain (PWS) and the more severe neurocutaneous Sturge–Weber syndrome (SWS) that is characterized by facial port-wine stains, and ocular and cerebral vascular malformations." (PMID 37658401, 2023). "Furthermore, the mechanism by which the mutated GNAQ/GNA11 genes induce capillary malformations is also still unknown, but there are several hypotheses." (PMID 35216474, 2022). "In the case of R183Q in GNAQ, hyperactive Gαq leads to hyperactivation of downstream pathways in endothelial cells, resulting in capillary malformations." (PMID 39687400, 2024). "Recently, the gene mutations of GNAQ and GNA11 have also been detected even in the lesions of sporadic capillary malformation." (PMID 35216474, 2022). "The capillary malformations seen in SWS and the more common isolated, uncomplicated capillary malformations are frequently found to have mutations in GNAQ or GNA11, which can lead to constitutive activation of the RAS/MAPK pathway." (PMID 33194911, 2020).
hemangioma (8 papers, 2019 to 2025). A benign vascular lesion characterized by the formation of capillary-sized or cavernous vascular channels. "Thrombotic hemangioma with organizing/anastomosing features (THOA) is a newly identified variant within the spectrum of hemangiomas that harbor mutations in the guanine nucleotide-binding protein alpha subunit (GNA) genes (like GNAQ or GNA11)." (PMID 39360118, 2024). "The results of these studies implicate that the essential mechanism underlying the pathogenesis of anastomosing hemangioma is related to GNAQ mutations, as well as its paralogues: GNA11 and GNA14." (PMID 39518110, 2024). "Our study identifies GNA14 Q205, GNA11 and GNAQ Q209 mutations as being the most common and mutually exclusive mutations in benign hemangiomas." (PMID 34040639, 2021). "The fourth cluster (black bar) is characterized by mutations resulting in GNAQ p.Q209 only (exception cherry angioma with one R183G mutation)." (PMID 31336681, 2019). "The role of GNAQ mutations helps distinguish low-grade angiosarcoma from anastomosing hemangiomas." (PMID 39130892, 2024). "In this article, we investigate the role of GNAQ and GNA11 mutations across varied disorders (e.g., UM, skin blue nevi, and hemangiomas), emphasizing the shared pathogenic mechanisms that connect them despite their differing clinical manifestations." (PMID 39518110, 2024). "The frequency of GNA gene mutations (GNAQ, GNA11 and GNA14) was highest with more than 52% in cases diagnosed as cherry (or senile) hemangioma." (PMID 34040639, 2021). "In line with two recently published cohorts of 85 hemangiomas, we also found GNA14 and GNAQ alterations to be the most common mutations in our cohort of benign vascular tumors." (PMID 34040639, 2021). "GNAQ, GNA11, and GNA14 (particularly GNA14 Q205L) mutations, which were mutually exclusive, were identified in approximately half of the cherry hemangiomas and cherry hemangioma-like hemangiomas." (PMID 39518110, 2024). "Recent studies have reported the presence of mutually exclusive mutations in GNA14 Q205, GNA11, and GNAQ Q209 in benign hemangiomas, but not in malignant vascular tumors, which supports the histologic impression of THOA." (PMID 39360118, 2024). "For cherry, congenital, anastomosing hemangioma, GNA14, GNA11 and GNAQ alterations have been described to be the most common alterations in these subtypes." (PMID 34040639, 2021). "A potential driving mechanism is that constitutive GTPase activity and the mitogen-activated protein (MAP) kinase signaling pathway are regulated by the recurrent mutant G protein alpha subunit GNAQ and its paralogs GNA11 and GNA14, which are also expressed in other hemangiomas." (PMID 40416971, 2025).
autoimmune disease (6 papers, 2016 to 2022). A disorder resulting from loss of function or tissue destruction of an organ or multiple organs, arising from humoral or cellular immune responses of the individual to their own tissue constituents. "Other targets of miR-21 are associated with immunity and the pathogenesis of autoimmune diseases such as SPRY1 (Sprouty RTK Signalling Antagonist 1), GNAQ (Guanine Nucleotide-Binding Protein Alpha-Q), PLEKHA1 (Pleckstrin Homology Domain Containing Family A), and CXCR4 (C-X-C Chemokine Receptor 4)." (PMID 27782053, 2016).
mucosal melanoma (6 papers, 2014 to 2025). A melanoma that arises from a mucosal site. "Major driver mutations in mucosal melanoma were detected in NRAS, KRAS, NF1, PTEN, GNAQ, and KIT." (PMID 39564955, 2024). "These genetic alterations are rarely observed in cutaneous or mucosal melanomas, suggesting that GNAQ and GNA11 may be involved in the early migration of melanocytes during embryogenesis, given GNAQ is important in melanocyte survival during early neural crest development." (PMID 41303082, 2025). "However, GNAQ or GNA11 mutations have not been reported in mucosal melanoma." (PMID 25030020, 2014).
rheumatoid arthritis (6 papers, 2016 to 2022). A chronic, systemic autoimmune disorder characterized by inflammation in the synovial membranes and articular surfaces. "In addition, rheumatoid arthritis (RA) patients showed an increase in GNAQ expression, especially in the synovial fluid." (PMID 36699722, 2022).
blue nevus (5 papers, 2016 to 2026). An intradermal nevus characterized by the presence of benign pigmented dendritic spindle-shaped melanocytes. "Blue nevus often harbors activating mutations in GNAQ and less frequently in GNA11." (PMID 39817262, 2025).
iris melanoma (5 papers, 2019 to 2025). A uveal melanoma that arises from the iris. "Iris melanoma harbor GNAQ, GNA11 and EIF1AX mutations while BAP1 mutations and mutations in SF3B1 are less common or rare." (PMID 33396957, 2020). "Iris melanoma, also originating from the uvea, has similarities to the genetic makeups of both posterior uveal melanoma (UM) and conjunctival melanoma since mutations in GNAQ and GNA11 are less common and genes involved in conjunctival melanoma such as BRAF have been described." (PMID 33396957, 2020). "GNAQ, Guanine nucleotide-binding protein subunit alpha-11 (GNA11), EIF1AX, and BAP1 are commonly identified mutations in iris melanoma." (PMID 40491523, 2025). "Mutations that are common in posterior UM such as GNAQ and GNA11 are described in iris melanoma but in lower frequency." (PMID 33396957, 2020). "GNAQ and GNA11 are mutually exclusive in iris melanomas, and the mutation status of GNAQ and GNA11 does, similar to UM, not correlate with patient survival." (PMID 32998469, 2020). "Genetic analysis confirmed our previous observation that patients harboring a wildtype BAP1 gene or who had a UV-damaged iris melanoma lived longer, regardless of their GNAQ/GNA11 mutational status." (PMID 37377898, 2023).
adenoma (4 papers, 2017 to 2023). A neoplasm arising from the epithelium. "More recently, overexpression of LHCGR required combined mutations of GNA11 and GNAQ in CTNNB1-mutant aldosterone-producing adenomas presenting in puberty, pregnancy or menopause." (PMID 36926028, 2023). "In the adenoma group, GNAQ, KRAS, MUC16, and TTN were identified as the driver genes, whereas in the cancer group, only GNAQ and KRAS were identified as the driver genes." (PMID 37546388, 2023).
Hypercalcemia (4 papers, 2017 to 2024). An abnormally increased calcium concentration in the blood. "Mice with biallelic germline deletion of Gna11 and parathyroid-specific loss of Gnaq alleles also developed hypercalcemia, strongly implicating GNAQ/11 signaling in extracellular calcium homeostasis in both humans and mice." (PMID 38618955, 2024).
leukemia (4 papers, 2013 to 2025). A malignant (clonal) hematologic disorder, involving hematopoietic stem cells and characterized by the presence of primitive or atypical myeloid or lymphoid cells in the bone marrow and the blood. "So far no activating mutations of GNAQ in leukemias have been reported." (PMID 24498620, 2013).
Venous malformation (4 papers, 2020 to 2025). A vascular malformation resulting from a developmental error of venous tissue composed of dysmorphic channels lined by flattened endothelium and exhibiting slow turnover. "We identified somatic variants within 26 of 44 (59%) individuals with slow-flow anomalies (either lymphatic malformation, venous malformation (VM), or mixed lymphatic/venous malformations) within the genes PIK3CA, TEK, GNAQ, BRAF, GNA11, and PIK3R1 with VAFs ranging between 0.7% to 24.8%." (PMID 39669602, 2024).
Ataxia (3 papers, 2013 to 2020). Ataxia refers to impaired coordination of voluntary muscle movement. "Among the 13 KEGG pathways that are differentially expressed, GNAQ appears in six pathways (Glutamatergic synapse, Endocrine and other factor-regulated calcium reabsorption, Circadian entrainment, Dopaminergic synapse, Gap junction, and Spinocerebellar ataxia)." (PMID 32722439, 2020).
CNS melanoma (3 papers, 2015 to 2025). "The authors reported 2 cases of children with melanoma of the CNS that presented mutations in the NRAS gene, and highlighted that melanoma of the CNS is associated with mutations in the GNAQ and GNA11 genes, whereas mutations in the NRAS gene are rare in adults." (PMID 26622814, 2015).
congenital hemangioma (3 papers, 2020 to 2025). A hemangioma present and fully formed at birth. "Somatic activating mutations in GNAQ and GNA11 have been identified in a subset of congenital hemangiomas." (PMID 33194900, 2020). "In congenital hemangioma, syndromic and non-syndromic capillary malformation mutations have been found on the guanine nucleotide-binding protein subunit alpha-11 (GNA11) or guanine nucleotide-binding protein G(q) subunit alpha (Gαq) (GNAQ) genes." (PMID 37830671, 2023).
neurocutaneous disorder (3 papers, 2025). "Sturge–Weber Syndrome (SWS) is a rare, sporadic neurocutaneous disorder affecting the skin, brain, and eyes, due to somatic activating mutations in GNAQ or, less commonly, GNA11 gene." (PMID 39819452, 2025). "Sturge–Weber Syndrome (SWS) is a rare neurocutaneous disorder caused by a somatic nonsynonymous mosaic mutation most commonly in the GNAQ gene (G protein guanine Nucleotide-binding protein Alpha subunit q)." (PMID 40217631, 2025).
nevus of Ota (3 papers, 2016 to 2024). "In the context of Ota nevus and ABNOM, melanocytes may acquire mutations in oncogenes, such as GNAQ (Guanine Nucleotide Binding Protein, Q Polypeptide), and enter this state of irreversible growth arrest." (PMID 39184811, 2024).
ocular melanoma (3 papers, 2014 to 2023). A melanoma that arises from the structures of the eye or ocular adnexa. "The genetic profile of CM differs from UM, another subtype of ocular melanoma, in which mutations in GNAQ/GNA11 are frequently described." (PMID 34071371, 2021). "Furthermore, GNAQ gene mutations have been identified in ocular melanoma, where they play a crucial role in tumor development and progression." (PMID 38023196, 2023).
vascular tumors (3 papers, 2021 to 2024). "With the exclusion of CM and SWS, which are mostly associated with GNAQ mutations affecting arginine 183 (p.R183), vascular tumors are linked to GNAQ/11/14 mutation at glutamine 209 (p.Q209) (or equivalent p.Q205 in GNA14)." (PMID 37024491, 2023). "Activating non-inherited mutations in the guanine nucleotide-binding protein G(q) subunit alpha (GNAQ) gene family have been identified in childhood vascular tumors." (PMID 37024491, 2023).